ALK (ALK receptor tyrosine kinase)
Diseases named in the same sentence as ALK in open-access papers (continued):
Sharing a sentence is not in itself a finding about the gene and the disease.
Renal cyst (7 papers, 2015 to 2025). A fluid filled sac in the kidney. "Crizotinib treatment appears to be associated with an increased risk of development and progression of renal cysts in patients with ALK-positive NSCLC." (PMID 25756473, 2015). "Continued treatment of ALK-positive NSCLC with crizotinib despite development of renal cysts was associated with ongoing tumor control, since RECIST-defined responses were maintained for a median of 14.0 months from treatment initiation in the 14 patients with objective responses." (PMID 25756473, 2015). "Renal cyst formation has been reported in patients treated with ALK inhibitors, especially those treated with the first-generation crizotinib." (PMID 39026680, 2024). "The first SAE report of a complex renal cyst in the crizotinib development program involved a 61-year-old (42-kg) Asian woman with ALK-positive NSCLC (patient 1)." (PMID 25756473, 2015). "The first serious adverse event (SAE) comprising a complex renal cyst developing during crizotinib treatment was reported in a phase II study of crizotinib 250 mg twice daily in patients with ALK-positive NSCLC (PROFILE 1005) in January 2011 (patient 1)." (PMID 25756473, 2015). "In this study, we reported a case of ALK-positive NSCLC with multiple renal cysts and renal dysfunction during crizotinib therapy and described the functional and pathological changes observed after long-term administration of crizotinib in an experimental mouse model." (PMID 30257437, 2018). "The results of the IRR conducted in 272 patients (255 treated with crizotinib and 17 with chemotherapy) from three clinical trials presented here represent the first large-scale systematic examination of the incidence of renal cysts in patients with ALK-positive NSCLC treated with crizotinib." (PMID 25756473, 2015). "In a retrospective study among thirty-two Taiwanese patients with ALK-positive NSCLC treated with crizotinib, seven patients presented renal cysts that regressed after drug withdrawal." (PMID 30257437, 2018). "A potential limitation of our study is the lack of comparison in evolution of renal cysts in ALK-rearranged NSCLC." (PMID 28209203, 2017). "There was not an apparent development of renal cysts in ALK-rearranged NSCLC patients who received chemotherapy on trial but larger population studies would be difficult to undertake given the efficacy and availability of crizotinib in this population moving forward." (PMID 28209203, 2017).
skin tumors (7 papers, 2013 to 2024). "Only breast and skin cancers have higher ALK mutation rates than NB, suggesting that ALK mutations play a more significant role in NB development than in other common cancer types." (PMID 34103089, 2021). "Epithelioid fibrous histiocytoma (EFH) is a type of uncommon skin tumor mostly harboring Anaplastic Lymphoma Kinase (ALK) gene rearrangement, with different fusion partners reported." (PMID 36648781, 2023). "In the 4th edition of the 2018 WHO classification of skin tumors, lesions in the spitzoid pathway (pathway 4) are characterized by mutations in HRAS, tyrosine kinase fusions (ALK, ROS1, RET, NTRK1/3, and MET), or serine-threonine kinase fusions (BRAF, MAP3K8)." (PMID 33040161, 2021). "It is interesting that each type of ALK-positive skin tumor seems to harbor a different common fusion gene." (PMID 29747676, 2018). "Lineage-specific immunohistochemistry is necessary to exclude other ALK-positive skin tumors, such as ALK+ALCL of the skin or Spitz tumor with ALK fusion." (PMID 29747676, 2018). "The structure of mouse skin features follicular differentiation of keratinocytes; hence skin tumour pathology of the ALK transgene is a reflection of this differentiation bias in mouse skin." (PMID 24163262, 2013).
thyroid (7 papers, 2014 to 2025). "MET, EML4, and ALK fusions also clustered with similar variables, along with the family history of thyroid diseases in general." (PMID 39409115, 2024). "On the contrary, our present thyroid IMT demonstrated the ALK-positive spindled cells." (PMID 29137037, 2017). "Although PTC is the most common thyroid malignancy in both pediatric and adult populations, established molecular differences—such as the predominance of BRAFV600E and RAS mutations in adults versus RET, NTRK, ALK, and MET alterations in children—may result in cytomorphological differences." (PMID 41462793, 2025). "Thyroid disease in the patient’s family, Hashimoto’s disease, and hypothyroidism, as well as the type of thyroidectomy, the need for indicating RAI, and smaller tumor size, clustered quite well with gene fusions related to RET, CCDC6, MET, EML4, and ALK." (PMID 39409115, 2024).
astrocytoma (6 papers, 2017 to 2022). "The present study clearly provided evidence that full-length ALK without any chromosomal rearrangements or gene mutations was frequently overexpressed in astrocytomas, particularly in GBMs." (PMID 28837676, 2017). "Immunoreaction for ALK (5A4) was mainly observed in cytoplasmic components of astrocytoma cells." (PMID 28837676, 2017). "ALK (5A4) immunopositivity (IHC score≧1) was evident in 9 (17.6%) of 51 GII, 5 (17.2%) of 29 GIII, and 29 (49.2%) of 52 GIV (GBM) astrocytomas, and the IHC scores were significantly higher in GBM as compared to those of GII and GIII tumors." (PMID 28837676, 2017). "The Kaplan-Meier curves for OS and PFS with respect to ALK (5A4) expression in astrocytomas showed that the patients with all grades of astrocytomas who displayed a lack of ALK (5A4) expression had more favorable OS and PFS as compared to the ALK (5A4)-immunopositive patients." (PMID 28837676, 2017).
autoimmune disease (6 papers, 2017 to 2025). A disorder resulting from loss of function or tissue destruction of an organ or multiple organs, arising from humoral or cellular immune responses of the individual to their own tissue constituents. "Some researchers believe that various factors, including trauma, inflammation, autoimmune diseases, surgery, viral infections, and abnormal expression or mutations of the anaplastic lymphoma kinase (ALK) gene, may contribute to the occurrence and development of IMT." (PMID 40260197, 2025). "Patients were excluded from the trial if they were harboring EGFR mutations or ALK translocations, had an Eastern Cooperative Oncology Group (ECOG) performance status ≥2, had untreated brain metastasis, or were receiving any dose of oral steroids for an autoimmune disease." (PMID 28285592, 2017). "Therefore, all patients with NSCLC without a contraindication (e.g., autoimmune diseases) or an actionable driver mutation (e.g., epidermal growth factor receptor [EGFR], anaplastic lymphoma kinase [ALK], or c‐ros oncogene 1 [ROS1]) should receive a PD(L)1i as part of their first‐line treatment." (PMID 35499294, 2022).
classic Hodgkin lymphoma (6 papers, 2015 to 2025). Classical Hodgkin lymphoma (CHL) is a B-cell lymphoma characterized histologically by the presence of large mononuclear Hodgkin cells and multinucleated Reed-Sternberg (HRS) cells. "Absence of ALK expression combined with various morphologies may constitute a diagnostic challenge for differential diagnosis with either CD30+ PTCL or classic Hodgkin lymphoma (CHL)." (PMID 34503066, 2021). "CD30 is a membrane glycoprotein from the tumor necrosis factor (TNF) receptor family and is frequently overexpressed in classical Hodgkin lymphoma (HL) and ALCL, with expression observed in 93–100% of cases in both ALK-positive and ALK-negative ALCL tumors." (PMID 41295262, 2025).
colon adenocarcinoma (6 papers, 2015 to 2024). "Although signet-ring histology has been associated with ALK-rearranged NSCLC, none of the reports identified signet-ring histology in the colon adenocarcinoma." (PMID 26172300, 2015).
malignant mesothelioma (6 papers, 2018 to 2024). A malignant neoplasm of the pleura or peritoneum, arising from mesothelial cells. "We found a female predominance, except for cases harboring NR4A3 and SUFU malignant mesothelioma, and most patients were around 60 years at diagnosis, but those harboring ALK or EWSR1/FUS::ATF1 gene fusions were younger." (PMID 39059063, 2024). "Malignant mesothelioma: typically shows positive staining for MC, CK5, and calcium-binding protein, but is negative for ALK." (PMID 39703852, 2024).
Rosai-Dorfman disease (6 papers, 2022 to 2025). "The pathologists should be aware of the rare diagnosis such as ALK positive large B-cell lymphoma, plasmablastic lymphoma and Rosai Dorfman disease in order to request requisite investigations." (PMID 36200017, 2022).
small cell carcinoma (6 papers, 2016 to 2024). A neuroendocrine carcinoma composed of small malignant cells which are often said to resemble "oat cells" under the microscope. "We identified 265 treatment-naïve patients with non-small-cell carcinoma, who had EGFR mutations (n = 159), KRAS mutations (n = 55), or ALK rearrangements (n = 51)." (PMID 27518729, 2016). "ALK positivity, defined based on an immunoreactivity score that takes both the intensity and the fraction of positive tumor cells into account, was identified in 12 tumors (1.5 %), including 11 adenocarcinomas and one non-small cell carcinoma NOS." (PMID 27495736, 2016).
soft tissue sarcoma (6 papers, 2017 to 2025). A malignant neoplasm arising from muscle tissue, adipose tissue, blood vessels, fibrous tissue, or other supportive tissues excluding the bones. "Our screen revealed promising combinations with EGFRis, such as the ALK/MET-inhibitor crizotinib, the HDAC-inhibitor panobinostat or the topoisomerase-II-inhibitor doxorubicin, which are part of standard chemotherapy regimens for various bone and soft-tissue sarcomas." (PMID 34550531, 2021).
urothelial carcinoma (6 papers, 2014 to 2025). A malignant neoplasm derived from the transitional epithelium of the urinary tract (urinary bladder, ureter, urethra, or renal pelvis). "As the incidence of ALK mutations in urothelial carcinoma is scarce, the potentiality of ALK inhibitors as therapeutic agents for urothelial carcinoma is considered to be limited." (PMID 40277792, 2025). "Currently, there is no information about ALK gene alterations in urothelial carcinoma (UC) and its correlation with clinical or pathologic features and outcome." (PMID 25083769, 2014). "Considering that ALK genomic alterations are rare and probably without prognostic implications in urothelial carcinoma, crizotinib may show antitumor activity against cisplatin-naïve and cisplatin-resistant BC by inhibiting the c-Met/PI3K/Akt pathway rather than the ALK pathway." (PMID 40277792, 2025).
viral infections (6 papers, 2014 to 2025). "We aim to describe a case of C-ALCL (anaplastic lymphoma kinase (ALK)−) in an elderly male who succumbed to the complication of associated HLH, which was possibly triggered by coexistent virus infection." (PMID 25405042, 2014).
Bradycardia (5 papers, 2016 to 2026). A slower than normal heart rate (in adults, slower than 60 beats per minute). "We also found that in terms of cardiac arrhythmias, ALK-TKIs mainly caused bradycardia-associated AEs." (PMID 35370632, 2022). "Oral inhibitors of ALK-positive tumors (e.g., crizotinib and ceritinib) were reported to cause sinus bradycardia." (PMID 35269958, 2022). "A meta-analysis suggested that the new generation of ALK inhibitors such as alectinib, brigatinib, or lorlatinib was associated with a similar risk of bradycardia when compared with crizotinib (estimated at around 8%), while the risk was lower during the ceritinib treatment." (PMID 35269958, 2022). "In addition, ALK inhibitors can cause hypogonadism and decreased testosterone levels may be associated with the development of bradycardia." (PMID 36535917, 2023). "The most severe phenotype was associated with immune checkpoint inhibitor-related myocarditis, whereas ALK inhibitors, thalidomide, antimetabolites-particularly 5-fluorouracil-and taxanes showed more reproducible signals for sinus bradycardia." (PMID 42192915, 2026). "Cardiac arrhythmia was a common adverse event of ALK-TKIs, especially bradycardia." (PMID 35370632, 2022). "Hence bradycardia, commonly observed during crizotinib treatment, may be a class effect of ALK inhibitors." (PMID 26823131, 2016).
carcinoids (5 papers, 2021 to 2024). "The ten ALK IHC positive specimens consisted of two typical carcinoids, two atypical carcinoids, and six SCLC." (PMID 35677534, 2022). "Within the retrospective cohort, NGS confirmed the presence of an ALK genomic rearrangement in one FISH-positive atypical carcinoid where material was sufficient for sequencing." (PMID 35756632, 2022). "Another patient with an atypical carcinoid with ALK-expression and ALK-rearrangement progressed after chemotherapy and was successfully treated with crizotinib." (PMID 35677534, 2022). "In the LCNEC and carcinoid cohort no rearrangements, no amplifications, no point mutations and no ALK expression was found." (PMID 35677534, 2022). "An atypical carcinoid with variant 3a/b ALK-rearrangement did not respond to crizotinib." (PMID 35677534, 2022).
chronic obstructive pulmonary disease (5 papers, 2016 to 2024). A chronic and progressive lung disorder characterized by the loss of elasticity of the bronchial tree and the air sacs, destruction of the air sacs wall, thickening of the bronchial wall, and mucous accumulation in the bronchial tree. "PD-L1 expression was significantly associated with male gender, co-existing chronic obstructive pulmonary disease (COPD), anaplastic lymphoma kinase (ALK) positivity, and advanced-stage tumors." (PMID 39583517, 2024). "*ECOGPS: Eastern cooperative oncology group performance status, COPD: Chronic obstructive pulmonary disease, EGFR: Epidermal growth factor receptor, ALK: Anaplastic lymphoma kinase." (PMID 39583517, 2024). "*PDL-1: Programmed cell death ligand-1, TPS: Tumor percentage score, ECOGPS: Eastern cooperative oncology group performance status, COPD: Chronic obstructive pulmonary disease, EGFR: Epidermal growth factor receptor, ALK: Anaplastic lymphoma kinase." (PMID 39583517, 2024).
cutaneous melanoma (5 papers, 2017 to 2025). A primary melanoma arising from atypical melanocytes in the skin. "Further, through the GEPIA database, in cutaneous melanoma, we examined the association between the ERBBs and 31 genes were close to each other and frequently altered and observed that all the genes except KIT, ALK, NTRK1, FGFR4, and MET were affected by the changes of some ERBB family members." (PMID 33732282, 2021).
histiocytic sarcoma (5 papers, 2021 to 2025). An aggressive malignant neoplasm with a poor response to therapy, usually presenting as stage III/IV disease. "The distinction between ALK- ALCL and anaplastic large B-cell lymphoma, histiocytic sarcoma, and monocytic sarcoma is readily established by immunohistochemistry." (PMID 34572893, 2021). "The differential diagnosis of ALK- ALCL includes ALK+ ALCL, other large PTCLs, CHL, anaplastic large B-cell lymphoma, monocytic sarcoma, and histiocytic sarcoma." (PMID 34572893, 2021).
hyperlipidemia (5 papers, 2022 to 2024). "The main cardiovascular adverse event of the third‐generation ALK inhibitor lorlatinib was hyperlipidemia." (PMID 36535917, 2023). "Despite being generally well tolerated, lorlatinib has a unique and challenging safety profile compared with other ALK-TKIs that is characterized by hyperlipidemia, cognitive effects, mood effects, oedema, and peripheral neuropathy which are documented by both FDA and EMA." (PMID 38903993, 2024). "As a third-generation ALK-TKI, lorlatinib has a distinct safety profile that is different from those of other ALK-TKIs, including hyperlipidemia, peripheral neuropathy, and central nervous system AEs." (PMID 38903993, 2024). "Consequently, lorlatinib should be strongly recommended for initial treatment of advanced ALK+ NSCLC; however, its long-term CNS adverse effects and cardiovascular toxicity resulting from hyperlipidemia necessitate evaluation over an extended duration." (PMID 38902768, 2024).
Interstitial pneumonitis (5 papers, 2021 to 2026). "Recently, a report characterized interstitial pneumonitis (IP) associated with ALK TKIs in the real world and indicated a fatal risk of IP induced by ALK TKIs." (PMID 39399468, 2024). "This is the first reported case of ensartinib-induced interstitial pneumonitis and illustrates a dissociation between tumor response and pulmonary toxicity, as well as sequential multiorgan toxicities during ALK TKI rechallenge." (PMID 42038652, 2026). "The EGFR and ALK dual inhibitor brigatinib reportedly induced similar early‐onset drug related interstitial pneumonitis." (PMID 33438350, 2021). "We report the case of a 50-year-old woman with advanced ALK-positive NSCLC who experienced rapid tumor regression after 1 month of treatment with ensartinib, complicated by mild bilateral interstitial pneumonitis." (PMID 42038652, 2026). "In advanced NSCLC, responses to ALK-TKI are typically seen within ~2 months.27) The NAUTIKA1 and ALNEO trials showed that 8 weeks of neoadjuvant alectinib achieved both efficacy and tolerability,26,28) although severe adverse events such as Grade 3 interstitial pneumonitis have been reported." (PMID 41036487, 2025).
juvenile xanthogranuloma (5 papers, 2024 to 2025). A benign histiocytic tumor that occurs during childhood; it is distinct from Langerhans cell histiocytosis. "Differential diagnosis with other types, such as ECD, Rosai-Dorfman disease (RDD), and systemic juvenile xanthogranuloma (JXG), remains difficult, relying primarily on clinical, pathological, and ALK fusion findings." (PMID 40700600, 2025).
lung adenosquamous carcinoma (5 papers, 2015 to 2023). "Our mouse model study shows that ALK overexpression is able to drive lung adenosquamous carcinoma development." (PMID 37051524, 2023). "Here, we report a case of lung adenosquamous carcinoma that recurred after surgical resection, harboring a novel 5′ NOK fusion form, ALK-CYP27C1, which benefited from the ALK inhibitor ensartinib." (PMID 36275795, 2022). "There are no reports on the effect of ALK inhibitors on ALK-positive lung adenosquamous carcinoma; therefore, its clinical course is unknown." (PMID 31030664, 2019).
Merkel cell carcinoma (5 papers, 2017 to 2025). "In a study of 32 cases of Merkel cell carcinoma, immunohistochemistry revealed ALK reactivity in 30 cases (93.8%)." (PMID 28895885, 2017). "RNA sequencing of 26 Merkel cell carcinomas has further identified ALK as the most frequently overexpressed gene among 50 cancer-related genes." (PMID 28895885, 2017). "ALK overexpression did not vary between MCV-positive and MCV-negative Merkel cell carcinoma, implying that ALK contributes to the disease independent of MCV infection." (PMID 28895885, 2017). "The possible role for of ALK in tumorigenesis presents a valuable opportunity to investigate the use of targeted therapies in its treatment—as either a primary or adjunctive strategy in control of Merkel cell carcinoma—which has, as-of-yet, not been addressed in the literature." (PMID 28895885, 2017).